SMIM28 (small integral membrane protein 28)
Gene: Protein-coding gene on chromosome 6 (138,377,905 to 138,383,486, forward strand). Ensembl gene ENSG00000262543.
Subcellular location: Membrane
Gene Ontology:
Cellular component: membrane
Homologues: Orthologues: chimpanzee SMIM28 (97% identical), macaque SMIM28 (95% identical), pig SMIM28 (77% identical), rabbit SMIM28 (70% identical).
Diseases named in the same sentence as SMIM28 in open-access papers:
SMIM28 is named in the same sentence as 4 diseases in open-access papers, as found by Europe PMC text mining. Sharing a sentence is not in itself a finding about the gene and the disease. The quoted sentences say what the papers report.
neuroblastoma (1 paper, 2020). Neuroblastoma (NB) is the most common solid, extracranial childhood tumor. "Further investigations are required to elucidate precisely the role of SMIM28 in the aggressiveness of neuroblastoma tumors." (PMID 33245713, 2020). "Nevertheless, additional studies are required to elucidate the role of SMIM28 in the pathogenesis of neuroblastoma." (PMID 33245713, 2020). "Functional studies are required to elucidate the roles of SMIM28, EVX2 and POU6F2 in high-risk neuroblastoma." (PMID 33245713, 2020). "Thus, it is possible that SMIM28 (Small Integral Membrane Protein 28) is part of a signalling pathway whose role is to accelerate neuroblastoma tumor proliferation, making it a possible new gene target therapy in high-risk neuroblastoma cancer." (PMID 33245713, 2020).
cancer (1 paper, 2020). A tumor composed of atypical neoplastic, often pleomorphic cells that invade other tissues. "The role of MAPK15 and UBC in tumorigenesis has been reported in many previously discussed scientific works, while SMIM28 is a less studied gene with an unclear role in cancer." (PMID 33245713, 2020).
tumor (1 paper, 2020). "We identified SMIM28 gene to be critical for tumor proliferation making it as a possible gene therapy target." (PMID 33245713, 2020). "SMIM28 was revealed to possibly have a role in tumor proliferation and aggressiveness." (PMID 33245713, 2020).
SMIM28 also shares sentences with these, for which no sentence is quoted: prostate carcinoma (1 paper).